DEGS1 (delta 4-desaturase, sphingolipid 1)
Diseases named in the same sentence as DEGS1 in open-access papers:
DEGS1 is named in the same sentence as 51 diseases in open-access papers, as found by Europe PMC text mining. Sharing a sentence is not in itself a finding about the gene and the disease. The quoted sentences say what the papers report.
Insulin resistance (14 papers, 2012 to 2025). Increased resistance towards insulin, that is, diminished effectiveness of insulin in reducing blood glucose levels. "Indeed, Degs1 deficiency improves insulin resistance and hepatic steatosis." (PMID 33991313, 2021). "4-HPR has been characterised as a competitive irreversible inhibitor of Degs1, which blocks ceramide accumulation in liver and skeletal muscle and reduces peripheral insulin resistance and hepatic steatosis in DIO mice." (PMID 33991313, 2021). "Knocking down dihydroceramide desulfurase 1 (Degs1) may improve insulin resistance and hepatic lipid accumulation in mice by reducing ceramide accumulation in mouse tissues, suggesting that ceramide accumulation is an important factor in causing disorders of glycolipid metabolism." (PMID 37513589, 2023). "In a recent study using diabetic mice, deletion of dihydroceramide desaturase 1 (DEGS1), an enzyme critical to the formation of ceramide from dihydroceramide, resolved hepatic steatosis and insulin resistance." (PMID 32914148, 2020).
Hepatic steatosis (10 papers, 2020 to 2025). Steatosis is a term used to denote lipid accumulation within hepatocytes. "Similarly, liver-specific ablation of the Degs1 gene encoding DES1 (or liver-targeted knockdown of Degs1 using shRNA) reversed high fat diet-induced hepatic steatosis." (PMID 32849291, 2020). "Deleting Degs1 from adult mice either prevented or reversed hepatic steatosis in ob/ob mice by blunting lipid uptake (via the fatty acid translocase CD36) and decreasing expression of lipogenic genes (e.g., Srebf1)." (PMID 32849291, 2020).
leukodystrophy (10 papers, 2019 to 2026). Leukodystrophies are a group of rare, progressive, metabolic, genetic diseases that affect the brain, spinal cord and often the peripheral nerves. "DEGS1 variants were found to be responsible for heterogeneous clinical pictures belonging to the family of hypomyelinating leukodystrophies." (PMID 38342436, 2024). "Very recently, several DEGS1 variants were described and reported to be responsible for clinical pictures belonging to the wide family of hereditary hypomyelinating leukodystrophies." (PMID 38342436, 2024). "Loss of function mutations in DEGS1 cause a hypomyelinating leukodystrophy, which is associated with increased plasma dihydrosphingolipids (dhSL) and with the formation of an atypical SPB 18:1(14Z);O2 metabolite." (PMID 37890668, 2023). "We recently reported that DEGS1 deficiency causes leukodystrophy and peripheral hypomyelination, which was associated with a pathologically increased formation of saturated dihydroSL species and the formation of an atypical monounsaturated d18:1 isomer." (PMID 31862735, 2020). "In addition, DEGS1 has been found to be involved in the metabolism of sphingolipid and adipocyte differentiation, be associated with many degenerative neurologic disorders such as leukodystrophy and play a role in the self-renewal of hematopoietic stem cells." (PMID 34332565, 2021). "More recently, a report studying individuals with hypomyelinating leukodystrophy in humans identified that the DEGS1 gene is involved in this disorder." (PMID 31915535, 2019). "This case expands the neuroimaging phenotype of DEGS1-related leukodystrophy and highlights intracranial calcifications, particularly within the cerebellum, as a potential diagnostic clue in the differential diagnosis of hypomyelinating disorders with conatal onset." (PMID 42260209, 2026). "Interestingly, some lysosomal storage disorders such as Krabbe disease and metachromatic leukodystrophy also show similar MRI phenotype to this DEGS1-mediated hypomyelinating leukodystrophy, thus the salvage pathway could be involved in this pathogenesis." (PMID 31915535, 2019).
neuroblastoma (7 papers, 2015 to 2025). Neuroblastoma (NB) is the most common solid, extracranial childhood tumor. "Similar effects on cell cycle regulation have been observed in neuroblastoma cells, where the inhibition of DEGS1 led to the accumulation of dhCer and resulted in cell cycle arrest during the G0/G1 phase." (PMID 40075756, 2025). "siRNA knockdown of DEGS1 or pharmacologically inhibiting DES with 4HPR, which increases dhCer, caused cell cycle arrest at G0/G1, and reduced Rb phosphorylation in human neuroblastoma cells." (PMID 37945603, 2023). "Inhibition of DEGS1 with siRNA in human neuroblastoma cells leads to the accumulation of endogenous dihydroceramides with subsequent effects on cell growth, particularly cell cycle arrest." (PMID 26528430, 2015). "Knockdown of the DEGS1 gene using small inhibitor RNA led to the accumulation of endogenous dihydroceramide, reduced cell growth and induced G1 cell cycle arrest in SMS-KCNR neuroblastoma cells." (PMID 33052246, 2020).
prostate carcinoma (6 papers, 2016 to 2026). A carcinoma that arises from epithelial cells of the prostate gland. "Multivariate Cox regression analysis combined with molecular docking studies identified DEGS1 as a gene potentially involved in the progression and drug resistance of prostate cancer." (PMID 40963603, 2025). "Western blot analysis demonstrated that DEGS1 expression was markedly upregulated in enzalutamide-resistant prostate cancer cells." (PMID 40963603, 2025). "To elucidate the biological function of DEGS1 in prostate cancer progression, we conducted a series of experiments." (PMID 40963603, 2025). "Integrating previous results of multivariate Cox analysis, DEGS1 may plays a key role in progression and drug resistance in prostate cancer." (PMID 40963603, 2025). "Furthermore, analysis of intracellular glucose consumption and lactate production indicated that DEGS1 enhances glycolytic activity in prostate cancer cells and may mediate lactylation regulation." (PMID 40963603, 2025). "Knockdown of DEGS1 significantly decreased the IC50 values of enzalutamide in both cell lines, underscoring the role of DEGS1 in the acquisition of enzalutamide resistance in prostate cancer." (PMID 40963603, 2025).
hypomyelinating leukodystrophy-18 (4 papers, 2023 to 2025). "In humans, mutations in the gene encoding DEGS1 cause a loss of the myelin sheath leading to a fatal neurodegenerative condition in children called hypomyelinating leukodystrophy-18." (PMID 40864161, 2025). "Thanks to the increased use of NGS, a growing number of pathogenic single nucleotide variants in DEGS1 have recently been reported to be responsible for hypomyelinating leukodystrophy 18 (HLD18), a rare and severe autosomal recessive form." (PMID 40371095, 2025). "Homozygous or compound heterozygous variants in DEGS1 have been associated with hypomyelinating leukodystrophy-18 (OMIM#:618404), an autosomal recessive neurologic disorder characterized by the onset of global developmental delay typically in early infancy." (PMID 37761828, 2023). "Likewise, malfunction of Δ4-dihydroceramide desaturase 1 (DEGS1), which converts dihydroceramide (DhCer) into Cer at the last step of this de novo pathway, causes severe hypomyelinating leukodystrophy-18 (HLD18) (OMIM #618404)." (PMID 36951944, 2023). "In humans, bi-allelic mutations in DEGS1 cause hypomyelinating leukodystrophy-18 (HLD-18), a progressive, often fatal pediatric neurodegenerative disease marked by cerebral atrophy, white matter reduction, and hypomyelination." (PMID 40864161, 2025). "Reduction of DEGS1 dihydroceramide desaturase function causes pediatric neurodegenerative disorder hypomyelinating leukodystrophy-18 (HLD-18)." (PMID 40864161, 2025). "Defects in DEGS1 cause the recently described hypomyelinating leukodystrophy-18 (HLD18) (OMIM #618404)." (PMID 36951944, 2023).
Obesity (4 papers, 2015 to 2023). Accumulation of substantial excess body fat. "In the obesity study, strong genetic control of body fat set-point as well as microbiome plasticity was unraveled, and multiple genetic loci were identified for obesity traits and dietary responses (e.g., Sptlc3, Klf14, Degs1, Npc, Cbr1, and amylases)." (PMID 26202330, 2015).
epilepsy (3 papers, 2021 to 2026). A brain disorder characterized by episodes of abnormally increased neuronal discharge resulting in transient episodes of sensory or motor neurological dysfunction, or psychic dysfunction. "Our findings also underscore the severe clinical course associated with DEGS1 deficiency, including profound developmental impairment, early-onset epilepsy, and persistent feeding difficulties." (PMID 42260209, 2026). "It has been reported that a variant in DEGS1 leads to a novel early-onset autosomal recessive complex neurological disease with Intelligent disability, progressive spastic paraplegia, scoliosis, and epilepsy." (PMID 34555062, 2021). "In this study, the present findings also revealed that DEGS1 was correlated with epilepsy." (PMID 34555062, 2021).
glioma (3 papers, 2021 to 2022). A benign or malignant brain and spinal cord tumor that arises from glial cells (astrocytes, oligodendrocytes, ependymal cells). "The overexpression of DEGS1 may divert the ceramides from the sphingolipid rheostat to other metabolic fates, correlating with a lower glioma patient survival." (PMID 36012521, 2022). "Furthermore, Δ9-tetrahydrocannabinol (THC), an active cannabinoid in Cannabis sativa L. plants, has also garnered much attention for its inhibition of DEGS1 in gliomas." (PMID 36012521, 2022).
pancreatic cancer (2 papers, 2018 to 2025). "DEGS1 is an intermediate enzyme in the synthesis of ceramide at the endoplasmic reticulum and the plasma membrane via the de novo pathway, and induces apoptosis in pancreatic cancer cells." (PMID 39478658, 2025). "To test whether changes in ceramide expression levels occur, we probed the ceramide de novo synthesis pathway by analyzing the expression of enzymes SPT, CERS-6, DEGS1 at 2, 4, and 6 hours after dosing with GT3, K-Ras mutated MIA PaCa-2 and Panc 1, and wild type BxPC3 pancreatic cancer cells." (PMID 29769046, 2018).
Cirrhosis (1 paper, 2016). A chronic disorder of the liver in which liver tissue becomes scarred and is partially replaced by regenerative nodules and fibrotic tissue resulting in loss of liver function. "Moreover, a cirrhosis risk score consisting of SNPs in 7 genes (AP3S2, AQP2, AZIN1, DEGS1, STXBP5L, TLR4, and TRPM5) has been shown to predict fibrosis progression in HCV infected patients." (PMID 26950933, 2016).
colitis (1 paper, 2023). Inflammation of the colon. "The effect of DEGS2 deletion in increasing susceptibility to DSS-induced colitis in mice with intact DEGS1 function indicates that DEGS2 has evolved a non-redundant function that cannot be performed by DEGS1." (PMID 37589563, 2023).
dysplasia (1 paper, 2022). A usually neoplastic transformation of the cell, associated with altered architectural tissue patterns. "All three enzymes showed significant increases from BE through dysplasia to EAC, but transcript levels of DEGS1 were decreased suggesting post‐translational regulation." (PMID 35560527, 2022).
myelogenous leukemia (1 paper, 2023). "To circumvent this problem, we generated DEGS1 KO cells via the CRISPR/Cas9 system using myelogenous leukemia-derived human HAP1 cells, which are near-haploid and therefore facilitate the easy generation of KO cells." (PMID 36907437, 2023).
ovarian carcinoma (1 paper, 2021). A malignant neoplasm originating from the surface ovarian epithelium. "The analysis of regulatory network involved in LASS6 showed that the high mRNAs of 7 key genes were associated with poor prognosis of OS in patients with ovarian cancer, among which DEGS1 was the most significant." (PMID 34488809, 2021). "Survival analysis showed that the high levels of SPHK1, KDSR, SMPD1, GALC, SMPD2, UGCG and DEGS1 were associated with poor prognosis of OS in patients with ovarian cancer, among which DEGS1 was the most significant (P = 3E-04)." (PMID 34488809, 2021). "In particular, the high expression of DEGS1, is significantly related to the poor prognosis (OS) of patients with ovarian cancer." (PMID 34488809, 2021).
preeclampsia (1 paper, 2023). Preeclampsia is a hypertensive disorder of pregnancy that is characterized by new-onset hypertension with proteinuria presenting after 20 weeks of gestation, and depending on mild or severe forms may initially present with severe headache, visual disturbances, and hyperreflexia. "Then, we performed LASSO and SVM-RFE and identified three critical diagnostic genes for preeclampsia, including CPOX, DEGS1 and SH3BP5." (PMID 38259465, 2023). "Then, we developed a novel diagnostic model using CPOX, DEGS1, and SH3BP5 and it showed a strong ability in screening preeclampsia samples from normal samples." (PMID 38259465, 2023). "The high expression of CPOX, DEGS1, and SH3BP5 may be associated with the pathogenesis of preeclampsia." (PMID 38259465, 2023). "In this study, we found that the expressions of CPOX, DEGS1 and SH3BP5 were highly expressed in preeclampsia samples in GSE44711 and GSE75010 datasets and our cohort." (PMID 38259465, 2023). "Compared to normal samples, preeclampsia samples showed markedly elevated expression of CPOX, DEGS1, and SH3BP5, as determined by RT-PCR." (PMID 38259465, 2023). "Importantly, the results of RT-PCR confirmed the expressions of CPOX, DEGS1 and SH3BP5 were distinctly increased in preeclampsia samples compared with normal samples." (PMID 38259465, 2023).
pulmonary arterial hypertension (1 paper, 2021). Pulmonary arterial hypertension (PAH) is a group of diseases characterized by mean pulmonary artery pressure >20 mmHg and elevated pulmonary arterial resistance leading to right heart failure. "MiR-244-5p/DEGS1 axis was initially investigated in this current study, which is expected to further the understanding of the etiology of pulmonary arterial hypertension." (PMID 34332565, 2021).
tricuspid atresia (1 paper, 2012). Tricuspid atresia is (TA) a rare congenital heart malformation characterized by the congenital agenesis of tricuspid valve leading to severe hypoplasia of right ventricle (functionally univentricular). "In fact, the functional synergy between both proteins was reduced by 50% over the DEGS1 promoter, which was recently shown by our group to be directly regulated by NFAT and HAND2 in chronic hypoxia, a mouse model mimicking cyanotic CHD including Tricuspid Atresia (unpublished data)." (PMID 23226213, 2012).
type 2 diabetes (1 paper, 2023). "Beyond this rare disease, intriguing emerging evidence associates DEGS1 expression and aberrant levels of Cer and/or DhCer with the appearance of comorbidities in the context of obesity, including type 2 diabetes, insulin resistance, and cardiovascular diseases." (PMID 36951944, 2023). "In this case, the knowledge gained could be applied to tackling more complex disorders, given the emerging role of DEGS1 in type 2 diabetes and cardiovascular disease." (PMID 36951944, 2023).
tumor (6 papers, 2016 to 2025). "Of the nine basal‐like‐associated cfRNA markers, five (PTTG2, RPL23AP7, UTS2, KDELC1, and DEGS1) were found to be overexpressed in basal‐like tumor tissue compared with tumors of the classical subtype within the HD tissue cohort." (PMID 39478658, 2025). "In this report, we also show that treatment with THC or inhibition of DEGS1 efficiently activates autophagy and apoptosis and inhibits tumor growth in mice." (PMID 27635674, 2016). "Inter-tumor variation in expression of the dihydroceramide Δ4-desaturases DEGS1 and DEGS2 that introduce a double bond in the sphingolipid backbone to generate ceramide, may also contribute to heterogeneity in the sulfatide saturation index in the iCCA group." (PMID 36630049, 2023). "Our data support the concept that the selectively increased expression of DEGS1 and ASAH1 in TSC tumor cells leads to increased sphingolipid biosynthesis, which in turn enhances TSC tumor cell viability and growth in preclinical models." (PMID 36927688, 2023). "Accordingly, followed by suppression of DEGS1 transcription and translation, SLC14A1 may also inhibit tumor growth/cell proliferation in UC-derived cells through hindering lipotoxicity." (PMID 33052246, 2020).
neurological disorders (3 papers, 2023 to 2025). "Unfortunately, they were not available for genetic testing, but this family history leads to speculating that a single hit in DEGS1 could be a risk factor for these neurological disorders." (PMID 40371095, 2025). "Abnormalities in the DEGS1 gene or protein may be associated with neurological disorders or other related health issues." (PMID 38259465, 2023).
neurodegenerative disease (2 papers, 2017 to 2025). A disorder of the central nervous system characterized by gradual and progressive loss of neural tissue and neurologic function. "Mutations in most members of the SPT complex, ceramide synthases, and DEGS1 lead to neurodegeneration, identifying the de novo ceramide biosynthesis pathway as a hotspot for neurodegenerative disease mutations." (PMID 40864161, 2025).
neurodevelopmental disorder (1 paper, 2023). A behavioral and cognitive disorder with onset during the developmental period that involves impaired or aberrant development of intellectual, motor, or social functions. "Since dual modes of inheritance have been observed in association with neurodevelopmental disorders of varying severity, the possibility of DEGS1 contributing to the patient’s phenotype remains viable and requires further investigation." (PMID 37761828, 2023).
DEGS1 also shares sentences with these, for which no sentence is quoted: cancer (14 papers); infection (9); atherosclerosis (2); developmental delay (2); diabetes (2); glioblastoma (2); Intellectual disability (2); metabolic disease (2); steatosis (2); breast carcinoma (1); cardiovascular diseases (1); congenital disorder of glycosylation (1); coronary artery disease (1); Flavivirus Infections (1); gastric cancer (1); hyperlipidemia (1); liver cancer (1); liver cirrhosis (1); lymph node metastasis (1); lysosomal disorders (1); metabolic syndrome (1); non-alcoholic fatty liver disease (1); peritonitis (1); prostate tumors (1); psoriasis (1); scoliosis (1); Spastic paraplegia (1); Tremor (1).